TPPP3 (tubulin polymerization promoting protein family member 3)
Description:
Regulator of microtubule dynamic that has microtubule bundling activity. Required for embryo implantation; possibly by regulating beta-catenin (By similarity). Also required for decidualization via regulation of beta-catenin.
Synonyms: CGI-38; p25gamma; p20; TPPP/p20
Tractability: PROTAC: its protein half-life has been measured.
Gene: Protein-coding gene on chromosome 16 (67,389,027 to 67,393,518, reverse strand). Ensembl gene ENSG00000159713.
Subcellular location: Cytoplasm; Cytoplasm, cytoskeleton
Gene Ontology:
Molecular function: tubulin binding
Biological process: decidualization; microtubule bundle formation; embryo implantation; microtubule polymerization; positive regulation of protein polymerization
Cellular component: cytoplasm; microtubule bundle; perinuclear region of cytoplasm; microtubule; cytoskeleton
Genetic constraint (gnomAD): Loss-of-function variants: 7 observed, 13.83 expected, observed/expected ratio (o/e) 0.51, 90% interval 0.29 to 0.95. The upper end of that interval is the gene's LOEUF score, 0.95, which puts it in group 4 of 6, group 1 being the genes least tolerant of losing a copy. Missense variants: 185 observed, 245.95 expected, observed/expected ratio (o/e) 0.75, 90% interval 0.67 to 0.85. Synonymous variants: 87 observed, 98.68 expected, observed/expected ratio (o/e) 0.88, 90% interval 0.74 to 1.05.
Homologues: Orthologues: chimpanzee TPPP3 (99% identical), macaque TPPP3 (98% identical), pig TPPP3 (97% identical), guinea pig TPPP3 (97% identical), mouse Tppp3 (97% identical), dog TPPP3 (96% identical), rat Tppp3 (96% identical), tropical clawed frog tppp3 (78% identical), zebrafish tppp3 (71% identical), Caenorhabditis elegans tppp-1 (39% identical), Drosophila melanogaster ringer (39% identical). Paralogues in human: TPPP (64% identical), TPPP2 (61% identical).
Diseases named in the same sentence as TPPP3 in open-access papers:
TPPP3 is named in the same sentence as 55 diseases in open-access papers, as found by Europe PMC text mining. Sharing a sentence is not in itself a finding about the gene and the disease. The quoted sentences say what the papers report.
colorectal cancer (5 papers, 2018 to 2025). A primary or metastatic malignant neoplasm that affects the colon or rectum. "HGSOC-F epithelial cells biomarker TPPP3 is a tubulin polymerization protein that has been previously implicated in colorectal cancer, while the other three genes are necessary for proper cilia function." (PMID 30383866, 2018). "Another protein, Tubulin polymerization-promoting protein family member 3, has been reported to be associated with the initiation and progression of colorectal cancer in humans, and its knockdown has been shown to inhibit cell proliferation and induce apoptosis." (PMID 41302034, 2025). "The shRNA-mediated knockdown of TPPP3 decreased cell proliferation in vitro and also decreased migration and invasion in colorectal cancer cell lines, LOVO and SW620." (PMID 41148789, 2025). "When looking at the effect of TPPP3 knockdown on angiogenesis, they found that in HUVEC cells, loss of TPPP3 resulted in fewer tube structures when these cells were treated with colorectal cancer cell-conditioned media." (PMID 41148789, 2025). "ShRNA knockdown of TPPP3 attenuated proliferation, invasion, and migration potential, as seen in breast cancer, colorectal cancer, and non-small-cell lung carcinoma." (PMID 41148789, 2025). "In this study, analysis of 96 patient samples compared to patient-matched healthy tissue revealed that TPPP3 was significantly increased in colorectal cancer." (PMID 41148789, 2025). "Our previous studies have shown that TPPP3 was upregulated in non-small-cell lung cancer and colorectal cancer." (PMID 33082910, 2020). "In 2017, it was reported that TPPP3 plays a similar role in colorectal cancer." (PMID 41148789, 2025). "Additionally, TPPP3 protein and mRNA levels were measured in five colorectal cancer cell lines compared to normal tissue and were significantly upregulated." (PMID 41148789, 2025). "Our previous studies demonstrated that TPPP3 could promote the development of colorectal cancer as well as non-small-cell lung cancer." (PMID 33082910, 2020). "TPPP3 modulates STAT3/Twist1 signaling in non-small-cell lung carcinoma and colorectal cancer, promoting proliferation, migration and invasion." (PMID 41148789, 2025).
glioblastoma (5 papers, 2020 to 2025). The most malignant astrocytic tumor (WHO grade IV). "Upregulation of TPPP3 has been linked to increased proliferation and invasion in glioblastoma cell lines, and CLDN11 has been reported to enhance invasiveness in small cell lung cancer." (PMID 41007824, 2025). "In 2019, a study to characterize rare genes in glioblastoma found TPPP3 contributed to worse overall survival and was associated with increased invasiveness." (PMID 41148789, 2025). "TPPP3 was also reported to be implicated in glioblastoma multiforme (GBM) progression and prognosis." (PMID 33082910, 2020). "Glioblastoma cell lines that overexpressed TPPP3 showed decreased levels of epithelial marker E-Cadherin and increased levels of mesenchymal markers, N-cadherin and Vimentin." (PMID 41148789, 2025). "In glioblastoma, TPPP3 expression is elevated as compared to normal tissue, and its expression appears to increase with the grade of the tumor." (PMID 41148789, 2025). "Transwell experiments suggested that in glioblastoma cell lines with low expression of TPPP3, the invasive ability of shTPPP3 glioblastoma cell lines had changed from weak to stronger if Snail1 protein was overexpressed." (PMID 37863960, 2023). "CCK8 results indicated that the proliferation rate of glioblastoma cells after TPPP3 overexpression was significantly higher than control group." (PMID 37863960, 2023). "The effect of TPPP3 knockdown on the migration and invasion of glioblastoma cells was evaluated by wound healing assay and Transwell assay." (PMID 37863960, 2023). "Up-regulation of TPPP3 expression in glioblastoma cells confer stronger ability of migration, invasion, proliferation and lower apoptosis in vitro." (PMID 37863960, 2023). "The content of this study paves the way for further in-depth exploration of the role of TPPP3 in glioblastoma in the future, and provides new treatment and research directions." (PMID 37863960, 2023). "The specific mechanism of TPPP3 regulating the malignant progression of glioblastoma was elaborated based on in vitro cytofunctional response experiments, and the correlation between TPPP3 and Snail1 was analyzed." (PMID 37863960, 2023). "Tubulin polymerization promoting protein 3 (TPPP3), a member of the tubulin polymerization family, participates in cell progressions in several human cancers, its biological function and the underlying mechanisms in glioblastoma multiforme (GBM) remain unclear." (PMID 37863960, 2023). "These in vivo experimental data further illustrate that TPPP3 inhibited the proliferation of glioblastoma cells and affected the EMT process." (PMID 37863960, 2023). "In order to more accurately describe the function of TPPP3 in the occurrence and malignant development of glioblastoma, we knocked down TPPP3 in U251 cells and verified the function of TPPP3 in vivo." (PMID 37863960, 2023). "In order to verify the biological function of TPPP3 on glioblastoma, we selected existing glioblastoma cell lines in the experiment for analysis." (PMID 37863960, 2023). "Wound healing experiments suggested similar results: When TPPP3 expression was increased, the migration ability of glioblastoma cells was significantly enhanced compared with the control group." (PMID 37863960, 2023). "To further explore the mechanistic role of TPPP3 in regulating glioblastoma cell invasion and migration, we knocked down TPPP3 in LN229 and U251 cells." (PMID 37863960, 2023). "Our research found that TPPP3 was an oncogene in glioma cells, which promoted the malignant biological behavior of glioblastoma cells." (PMID 37863960, 2023). "After the analysis of clinical data, we learned that there was a positive correlation between TPPP3 and Snail1, and the role of TPPP3 in the survival of glioblastoma patients was also presented." (PMID 37863960, 2023).
glioblastoma (continued). "This study will pave the way for further exploration of the role of TPPP3 in glioblastoma, provide direction and ideas, and provide theoretical evidence for TPPP3 to become a potential therapeutic target for glioblastoma." (PMID 37863960, 2023). "In clinical data analysis, we found a positive correlation between TPPP3 and Snail1 protein expression levels in glioblastomas." (PMID 37863960, 2023). "The biological role of TPPP3 in malignant progression of glioblastoma was further clarified by in vivo experiments." (PMID 37863960, 2023). "We randomly selected 5 pairs of glioblastoma and normal brain tissues for Western blot experiments, and the results suggested that TPPP3 was more highly expressed in tumor tissues." (PMID 37863960, 2023). "our study found relevant mechanisms of TPPP3 regulating tumor cell migration, invasion, proliferation, apoptosis and EMT transformation in glioblastoma, and discussed the correlation and association between TPPP3 and EMT marker protein Snail1 in detail." (PMID 37863960, 2023). "Recently, higher RNA and/or protein TPPP3 levels have been found in glioblastoma, breast cancer, melanoma stem cells and endometrial cancer as well where the higher TPPP3 expression levels are associated with poorer outcome and worse overall survival." (PMID 36230985, 2022). "In glioblastoma, TPPP3 affects the Snail pathway, a common marker of EMT." (PMID 41148789, 2025). "TPPP3 has also been associated with stemness and EMT in glioblastoma." (PMID 41148789, 2025). "While our results revealed that TPPP3 played a key role in glioblastoma EMT, the deeper mechanism remains unclear." (PMID 37863960, 2023). "To assess whether the effect of TPPP3 on glioblastoma motility is related to EMT, we examined the expression of EMT-related markers (Vimentin, N-cadherin, e-cadherin)." (PMID 37863960, 2023). "Up-regulation of TPPP3 expression in glioblastoma cells may confer stronger ability of migration, invasion, proliferation and lower apoptosis in vitro." (PMID 37863960, 2023). "Low TPPP3 expression leads to better survival expectations in glioblastomas patients." (PMID 37863960, 2023). "This further clarified the biological role of TPPP3 in the malignant progression of glioblastoma." (PMID 37863960, 2023). "However, we still need more evidence to support the application value of TPPP3 in glioblastoma, and the detailed mechanism of its participation in the malignant biological behavior of glioblastoma needs to be explored." (PMID 37863960, 2023). "Finally, clinical data were used to analyze the effect of TPPP3 on the survival of glioblastoma patients." (PMID 37863960, 2023). "TPPP3 knockdown could inhibit the proliferation, migration and, invasion and induce apoptosis of glioblastoma cells, that could be largely reversed after Snail1 up-regulation." (PMID 37863960, 2023). "TPPP3 expression was found higher in glioblastoma cell lines than in human normal astrocytes (NHA)." (PMID 37863960, 2023). "Then, different glioblastoma cell lines were used to carry out related in vitro cell function experiments and detection of malignant behavior-related proteins to verify the effect of TPPP3 on the proliferation, apoptosis, migration and invasion of glioblastoma cells." (PMID 37863960, 2023). "We randomly selected some glioblastoma tissue with high and low expression of TPPP3." (PMID 37863960, 2023). "In addition, 96 h CCK-8 assay showed that the proliferation ability of glioblastoma cells with TPPP3 knockdown was significantly reduced compared with control cells." (PMID 37863960, 2023). "At the same time, we conducted survival analysis on the existing data and found that among glioblastoma patients, patients with low TPPP3 expression had a longer progression-free survival, and the overall survival rate was higher than that of the high TPPP3 group." (PMID 37863960, 2023). "Our results suggest that TPPP3 may have a role in glioblastoma." (PMID 37863960, 2023).
glioblastoma (continued). "Inhibition of TPPP3 expression in GBM could reduce the migration, invasion, proliferation and induce the apoptosis of glioblastoma cells." (PMID 37863960, 2023). "Therefore, exploring the influence of TPPP3 on the malignant phenotype of glioblastoma cells can provide a new entry point for us to deal with the refractory of GBM." (PMID 37863960, 2023).
breast carcinoma (4 papers, 2020 to 2025). "Single cell RNA sequencing of breast cancer lung metastases in mice revealed a subpopulation of Tppp3+ monocytes that are highly associated with the metastases, likely through the promotion of angiogenesis." (PMID 41148789, 2025). "In breast cancer, loss of TPPP3 is also associated with decreased proliferation, migration and invasion." (PMID 41148789, 2025). "Additionally, TPPP3 has also been shown to be associated with breast cancer lung metastasis through Tppp3+ monocytes." (PMID 41148789, 2025). "Silencing of TPPP3 in breast cancer cell lines MCF-7 and T47D decreased cell proliferation, invasion and migration." (PMID 41148789, 2025). "NF-κB p65, also known as RelA, and COX2 expressions were also significantly downregulated after TPPP3 silencing, indicating that interfering with TPPP3 alters the malignant phenotype of breast cancer by downregulating the NF-κB/COX2 pathways." (PMID 41148789, 2025). "We have identified four mouse myeloid subpopulations that highly correlate with breast cancer metastasis to lung, including Tppp3+ monocytes, Isg15+ macrophages, Ifit3+ neutrophils, and Il12b+ DCs." (PMID 37483625, 2023). "According to the results of the Oncomine database, we found that TPPP3 was lower expressed in breast cancer, head and neck cancer, kidney cancer, ovarian cancer, and sarcoma compared to normal tissues, while higher expression in gastric cancer." (PMID 33083464, 2020). "In breast cancer, TPPP3 is also involved in cell proliferation, invasion, and metastasis." (PMID 41148789, 2025). "This could potentially inform research about the role of TPPP3 in cancer, given it is already associated with NF-kB/COX2 pathways in breast cancer." (PMID 41148789, 2025). "Comparing to normal tissues, the study demonstrated that TPPP3 observed lower expression in bladder cancer, brain cancer, breast cancer, head and neck cancer, kidney cancer, lung cancer, melanoma, ovarian cancer, and sarcoma and high expression in gastric cancer." (PMID 33083464, 2020). "Obviously, proportions of ISG15+ macrophages and IFIT3+ neutrophils in primary tumor have low levels as that in normal lung but not TPPP3+ monocytes and IL12B+ DCs, which indicate that these myeloid subpopulations may have different degrees of association with breast cancer metastasis to lung." (PMID 37483625, 2023).
endometrial cancer (3 papers, 2020 to 2025). Primary or metastatic malignant neoplasm involving the endometrium (mucous membrane that lines the endometrial cavity). "Loss of TPPP3 in endometrial cancer also resulted in decreased proliferation, migration, and invasion; however, a mechanism was not proposed." (PMID 41148789, 2025). "Conversely, overexpression of TPPP3 in endometrial cancer cells with induced miR-1827 expression is able to maintain their proliferative, invasive, and migrative potential." (PMID 41148789, 2025). "When compared to normal endometrial tissue, endometrial cancer cell lines, as well as patient samples, exhibited elevated levels of TPPP3." (PMID 41148789, 2025). "In addition to proliferation and metastasis, they also investigated how overexpression of microRNA 1827 (miR-1827) affects TPPP3 expression in endometrial cancer." (PMID 41148789, 2025).
Lewis Lung Carcinoma (3 papers, 2017 to 2023). "Further depletion of TPPP3 in HeLa cells resulted in multiple abnormalities during mitosis leading to cell death and depletion of TPPP3 in Lewis Lung Carcinoma cells inhibited tumour growth and metastasis." (PMID 28931065, 2017). "Furthermore, TPPP3 silencing could inhibit the growth of HeLa and Lewis lung carcinoma cells." (PMID 33082910, 2020).
melanoma (3 papers, 2020 to 2022). A malignant, usually aggressive tumor composed of atypical, neoplastic melanocytes. "Collectively, it could be concluded that hnRNP A2B1 promoted tumorigenesis of melanoma stem cells via regulating the splicing of the precursor mRNAs of TPPP3, DOCK2, EIF3H, RNF128, DAPK1, and SYT7." (PMID 33509274, 2021). "On the other hand, the hnRNP A2B1 overexpression resulted in significant upregulations of TPPP3, EIF3H, and DOCK2 and downregulations of DAPK1, RNF128, and SYT7 in melanoma stem cells." (PMID 33509274, 2021). "The in vivo data indicated that hnRNP A2B1 was required for tumorigenesis by affecting the splicing of TPPP3, DOCK2, EIF3H, RNF128, DAPK1, and SYT7, thus suppressing apoptosis of melanoma stem cells." (PMID 33509274, 2021). "Our findings revealed that the hnRNP A2B1-mediated splicing triggered the upregulation of TPPP3, DOCK2, and EIF3H, and the downregulation of RNF128, DAPK1, and SYT7 in melanoma stem cells, leading to the suppression of apoptosis of cancer stem cells." (PMID 33509274, 2021). "In this study, the results showed that hnRNP A2B1 suppressed apoptosis of melanoma stem cells through post-transcriptional regulation of apoptosis-related DAPK1, SYT7, RNF128, EIF3H, TPPP3, and DOCK2 genes." (PMID 33509274, 2021). "Taken together, these findings revealed that hnRNP A2B1 played a positive role in tumorigenesis of melanoma stem cells in vivo by affecting the splicing of TPPP3, DOCK2, EIF3H, RNF128, DAPK1, and SYT7, thus suppressing apoptosis of melanoma stem cells." (PMID 33509274, 2021). "Western blot data indicated that the hnRNP A2B1 silencing led to significant downregulations of TPPP3, EIF3H, and DOCK2 and upregulations of DAPK1, RNF128, and SYT7 in melanoma stem cells compared with the control." (PMID 33509274, 2021). "Northern blot data indicated that TPPP3, DOCK2, and EIF3H were significantly upregulated in melanoma stem cells compared with cancer non-stem cells, while RNF128, DAPK1, and SYT7 were downregulated in melanoma stem cells." (PMID 33509274, 2021).
alpha-synucleinopathies (2 papers, 2022 to 2025). "TPPP3 has also been investigated in the context of neurodegenerative disease, specifically in the context of alpha-synucleinopathies." (PMID 41148789, 2025). "Although the strong affinity to TPPP1 resulted in the destruction of the TPPP1- α-synuclein complexes that promote these diseases, TPPP3 may have an inhibitory effect in alpha-synucleinopathies." (PMID 41148789, 2025). "However, the aggregation-promoting activity is characteristic only of TPPP1, but not of TPPP3; the former is involved in the development of neurodegenerative disorders, namely synucleinopathies." (PMID 36230985, 2022).
endothelial dysfunction (2 papers, 2020 to 2025). In vascular diseases, endothelial dysfunction is a systemic pathological state of the endothelium (the inner lining of blood vessels) and can be broadly defined as an imbalance between vasodilating and vasoconstricting substances produced by (or acting on) the endothelium. "In this review, we summarize the current findings on TPPP3 and its dysregulation in various diseases including cancer, reproductive dysfunction, musculoskeletal conditions, endothelial dysfunction, and neurodegenerative diseases." (PMID 41148789, 2025). "Since TPPP3 could enhance the stabilization of VDAC1, the roles of VDAC1 in TPPP3-medicated endothelial dysfunction were explored in TPPP3 overexpressed HUVEC." (PMID 33082910, 2020).
head and neck cancer (2 papers, 2020 to 2025). A primary or metastatic malignant neoplasm affecting the head and neck. "There are multiple head and neck cancers where tumor samples had lower TPPP3 expression than the surrounding area and was correlated with worse survival." (PMID 41148789, 2025).